USP4 (ubiquitin specific peptidase 4)
Diseases named in the same sentence as USP4 in open-access papers (continued):
Sharing a sentence is not in itself a finding about the gene and the disease.
tumor (continued). "In CRC tissues, USP4 has been found to stabilize PRL-3 by deubiquitinating PRL-3, activating PI3K/AKT pathway and down-regulating E-cadherin, thereby promoting tumor proliferation and metastasis." (PMID 37251574, 2023). "In vitro and in vivo studies also propose USP4 as a selective regulator of TGF-β/SMAD signaling in mammalian cells and zebrafish embryos that plays a critical role in the tumor-inducing arm of the TGF-β/SMAD pathway." (PMID 33946990, 2021). "In line with these, depletion of macrophages with clodrondate liposomes inhibited tumor growh of LLC cells, reduced the expression of Snail1 and increased the expression of USP4 in tumors." (PMID 31936290, 2020). "USP4 interacted with tricho-rhino-phalangeal syndrome type I to form a complex which led to HDAC2 deubiquitination, then promoted tumor growth both in vitro and in vivo." (PMID 32669974, 2020). "Further study indicated that USP4 can target and deubiquitinate PCD4 which led to a tumor-suppressing effect." (PMID 32669974, 2020). "Taken together these results led to a mechanistic scheme in which TRPS1 scaffolding recruits USP4 to de-ubiquitinate and stabilize HDAC2, leading to repression of a set of anti-growth genes and acceleration of tumor growth." (PMID 30071870, 2018). "These scenarios fit well with our working model that TRPS1 recruits USP4 to stabilize HDAC2 and represses expression of AES, Casp7, PERP, and ZW10 to confer tumor growth." (PMID 30071870, 2018). "Subsequently, thirty paired specimens were selected to explore the USP4 expression level in HCC and matched non-tumor tissues using quantitative real-time PCR (qRT-PCR)." (PMID 29396555, 2018). "Next, immunohistochemical (IHC) staining of USP4 in a tissue microarray that included 80 pairs of HCC and matched non-tumor tissues was performed." (PMID 29396555, 2018). "We observed a similar trend in which patients with high USP4 expression had a shorter OS time than those with low expression when further OS analysis was performed based on the UICC stage and tumor relapse." (PMID 29396555, 2018). "In univariate analysis of OS and cumulative recurrence, USP4 expression, serum AFP level, vascular invasion, and tumor size emerged as significant independent prognostic factors (P < 0.05 for all)." (PMID 29396555, 2018). "Our working model suggests that TRPS1 recruits USP4 to stabilize HDAC2 repressing the expression of AES, Casp7, PERP, and ZW10 to confer tumor growth." (PMID 30071870, 2018). "Nevertheless, our observation that TRPS1 recruits USP4 to de-ubiquitinate HDAC2 extends the current knowledge on the regulation of HDAC2 stability by the ubiquitin system, contributing to tumor growth." (PMID 30071870, 2018). "USP4 and S1P1 were up-regulated in mesenchymal-type liver-tumor cells with miR-148a dysregulation, facilitating migration and proliferation of tumor cells." (PMID 24798342, 2014). "In the subsequent experiments, we determined the role of USP4, S1P1, or miR-148a in tumor cell migration and growth." (PMID 24798342, 2014). "Furthermore, USP4 101 and DUB3 98 stabilize Snail and induce EMT, thereby promoting HCC cell migration, invasion, and tumor metastasis in vitro and in vivo." (PMID 41208892, 2025). "In HNSCC, USP4 is upregulated compared to non-cancerous tissue and has tumor suppressor qualities in vitro." (PMID 37308746, 2023). "The phosphorylation of USP4 prolongs its half-life on the plasma membrane, and activates TGF-β cell signalling through binding and deubiquitination of TGF-β receptors, which plays a crucial role in tumour cell migration and metastasis." (PMID 34177595, 2021). "USP4, a member of the USP family, is also closely related to tumor progression." (PMID 30335615, 2018).
tumor (continued). "In this study, we report that TRPS1, USP4, and HDAC2 form a regulatory axis to confer tumor growth." (PMID 30071870, 2018). "Therefore, we performed IHC assays to detect the expression of USP4, TGFR-1 and EMT markers in HCC tumor tissues and analyze their correlation." (PMID 30335615, 2018). "First, tissue microarray data demonstrated that high USP4 expression was positively associated with distant metastasis and poor survival in HCC patients, suggesting that USP4 plays a more important role in HCC invasion and metastasis than in tumor cell proliferation." (PMID 30335615, 2018). "Previous studies have shown that USP4 deubiquitinates and regulates TGFR-1 in other tumor types." (PMID 30335615, 2018). "Significantly, our results revealed the scaffolding function of TPRS1 in USP4-directed HDAC2 de-ubiquitination and provided new mechanistic insights into the crosstalk between TRPS1, ubiquitin, and histone modification systems leading to tumor growth." (PMID 30071870, 2018). "Interestingly, many of these USP4 loss-of-function mutations, including L301R, S315C and R559W, are found mainly located in the catalytic domain of USP4, suggesting that the DUB activity is critical for maintaining BRCA1 stability and hence its tumor suppression function." (PMID 38734703, 2024). "Further, the effect of USP4 on biological function investigated in HCC cell lines showed that USP4 knockdown significantly impaired HCC cell proliferation, colony formation, migration, and invasion in vitro and inhibited tumor growth and intrahepatic metastasis in vivo." (PMID 29396555, 2018). "Clinically, we found that USP4 is overexpressed in human HCC tissues compared with adjacent non-tumoral tissues and is significantly correlated with malignant phenotype characteristics, including tumor size, tumor number, differentiation, serum alpha-fetoprotein level, and vascular invasion." (PMID 29396555, 2018).
infection (3 papers, 2015 to 2023). The state of being infected such as from the introduction of a foreign agent such as serum, vaccine, antigenic substance or organism. "Based on the mass spectrometric analysis, the THP-1 macrophages infected with Y. enterocolitica for 2 hours post-infection (hpi) had an increased level of USP4 and USP7 but decreased level of OTUD6B." (PMID 37026055, 2023). "Western blot and q-PCR analysis confirmed that the expression of USP4 was significantly downregulated 8 h, 12 h, and 24 h post-infection (p.i)." (PMID 30194441, 2018). "We identified new chicken DUBs on the basis of the reaction with the Ub-VS probe and characterized USP4, USP5, UCH-L3 and UCH-L5 as DUBs regulated in infection." (PMID 26267804, 2015). "This infection did not lead to significant changes in deubiquitinase levels/activity at 2 hpi, apart from the downregulation of USP4." (PMID 37026055, 2023).
immune disease (2 papers, 2021). "USP4 is a deubiquitinating enzyme and plays an important role in tissue fibrosis and immune disease." (PMID 33295107, 2021).
metabolic disease (2 papers, 2021). A congenital disorder (due to inherited enzyme abnormality) or acquired (due to failure of a metabolically important organ) disorder resulting from an abnormal metabolic process. "Thus, USP4 functions as a pivotal suppressor in NAFLD and related metabolic disorders." (PMID 33681193, 2021).
adenocarcinoma (1 paper, 2023). A common cancer characterized by the presence of malignant glandular cells. "However, in contrast to our results, USP4 prevailed as an independent prognostic factor for adenocarcinoma patients after correction for confounders in multivariable analysis of overall and disease-free survival." (PMID 37308746, 2023).
bacterial infections (1 paper, 2021). "Aberrant regulation of USP4 has also been reported in viral and bacterial infections." (PMID 33681193, 2021).
USP4 also shares sentences with these, for which no sentence is quoted: pancreatic cancer (3 papers); autoimmune disorders (1); breast (1); breast tumor (1); Cirrhosis (1); Hepatitis (1); hypertriglyceridemia (1); liver cirrhosis (1); lupus nephritis (1); lymph node metastases (1); neurodegenerative disease (1); nevus (1); oropharyngeal carcinoma (1); oropharyngeal squamous cell carcinoma (1); ovarian tumors (1); Salmonella Infections (1); small cell lung carcinoma (1); squamous cell lung carcinoma (1); triple-negative breast carcinoma (1).